KLC1 (kinesin light chain 1)
Diseases named in the same sentence as KLC1 in open-access papers (continued):
Sharing a sentence is not in itself a finding about the gene and the disease.
Dystonia (1 paper, 2025). An abnormally increased muscular tone that causes fixed abnormal postures. "Screening our data for proposed dystonia candidate genes identified presumably pathogenic variants in CHD6, KCNN2, KLC1, NR4A2, and ZMYND11, but not in others, for example, ATP5F1B, ACBD6, CIZ1, SHQ1, and SPTBN1." (PMID 40533913, 2025). "Notably, our data support a role of pathogenic variants in CHD6, KLC1, NR4A2, and ZMYND11 in dystonia even without neurodevelopmental features, while the relevance of identified VUS in several candidate genes remains unclear." (PMID 40533913, 2025).
endometrial carcinoma (1 paper, 2024). A malignant tumor arising from the epithelium that lines the cavity of the uterine body. "In conclusion, our findings strongly support the integration of EIF4G2, KIF5B and KLC1 markers into clinical practice for the management of endometrial carcinoma." (PMID 38388710, 2024).
focal dystonia (1 paper, 2025). A dystonia that is localized to a specific part of the body. "For KLC1 and NR4A2, five and four additional patients, respectively, with similar phenotypes of adult‐onset focal dystonia, carried VUS." (PMID 40533913, 2025).
glaucoma (1 paper, 2020). Increased pressure in the eyeball due to obstruction of the outflow of aqueous humor. "It is important to note that some of our positional candidates—Eif5, Bag5, Klc1, and Ppp1r13b—have been previously demonstrated to play a role in glaucoma and/or RGC health." (PMID 32174956, 2020).
lung adenocarcinoma (1 paper, 2012). A carcinoma that arises from the lung and is characterized by the presence of malignant glandular epithelial cells. "KLC1-ALK may be rare but exists in lung adenocarcinoma, and the patients with this fusion are highly likely to benefit from ALK inhibitor therapy as do patients with other ALK fusions." (PMID 22347464, 2012).
neuroendocrine carcinoma (1 paper, 2022). A malignant neuroendocrine neoplasm composed of cells containing secretory granules that stain positive for NSE and chromogranin. "An LCNEC and AC showed an EML4-ALK fusion, and the high-grade neuroendocrine carcinoma, a KLC1-ALK fusion." (PMID 35756632, 2022).
osteoporosis (1 paper, 2021). A condition of reduced bone mass, with decreased cortical thickness and a decrease in the number and size of the trabeculae of cancellous bone (but normal chemical composition), resulting in increased fracture incidence. "The increased expression of hsa_circ_0042409 regulated the expression level of KLC1 by spongy hsa-mir-195-5P, thus promoting the pathogenesis of osteoporosis." (PMID 34123587, 2021). "qPCR showed that the expression level of circRNA hsa_circ_0042409 and KLC1 mRNA was significantly increased in male osteoporosis patients, while that of hsa-miR-195-5p was significantly decreased with the cutoff of P-value < 0.05 compared to healthy controls." (PMID 34123587, 2021).
cancer (6 papers, 2020 to 2025). A tumor composed of atypical neoplastic, often pleomorphic cells that invade other tissues. "KLC1 has been implicated in various cancer types by interacting with other proteins." (PMID 38923999, 2024). "KLC1 exhibits extensive alternative splicing, generating isoforms with distinct C-termini that bind to different proteins and play critical roles in cancer cells." (PMID 40228435, 2025). "Through its interactions with other proteins, KLC1 also plays a role in the development and progression of a number of cancers as well as neurodegenerative illnesses." (PMID 40421300, 2025). "KLC1 was significantly reduced in both cancer cell lines, while DYNC1I1 had notably higher protein amounts in PC-3 compared to LNCaP cells." (PMID 39217195, 2024). "TOP2A and KLC1 were the most frequently expressed of the upregulated protein in SaOS mutants, overexpressed in many cancers with TOP2A and expressed in many healthy tissues." (PMID 36010968, 2022). "Heatmap results showed that NRP1, MFAP2, KLC1, DST, and MYOZ3 were generally downregulated in cancer cell lines, while KIF21B, SRI, INCENP, and KEAP1 were also downregulated." (PMID 40228435, 2025).
infection (4 papers, 2012 to 2021). The state of being infected such as from the introduction of a foreign agent such as serum, vaccine, antigenic substance or organism. "Unexpectedly, this revealed that during infection A36 interacts almost exclusively with KLC1." (PMID 28485852, 2017). "Using full‐length KLCs and a full‐length A36 expressed at natural levels during infection, the interaction was specific for KLC1 and practically absent from KLC2." (PMID 28485852, 2017). "Infection of 3T3 cells with the virus expressing KLC1-ALK readily produced multiple transformed foci in culture and subcutaneous tumors in a nude mouse tumorigenicity assay, confirming the potent transforming ability of KLC1-ALK." (PMID 22347464, 2012). "The experiment was repeated during infection using either wt VACV or mutants lacking F12 (vΔF12) or E2 (vΔE2), but under the conditions tested no change in KLC1/A36 interaction was seen." (PMID 28485852, 2017).
tumor (3 papers, 2022 to 2024). "Overall, these results show a strong correlation between low protein expression of either KLC1 or KIF5B and poorer survival outcomes in specific EC tumor classes." (PMID 38388710, 2024). "Out of all the candidates, KLC1 and TOP2A showed high levels of expression in every tumor type examined." (PMID 36010968, 2022).
neurodegenerative disease (2 papers, 2009 to 2024). A disorder of the central nervous system characterized by gradual and progressive loss of neural tissue and neurologic function. "Later studies showed that KIF and KLC1 implicated axoplasmic transport is disrupted in AD and axonal transport in general is significantly associated with neurodegenerative diseases." (PMID 39251023, 2024). "Genes involved in neurodegenerative diseases, kinesin light chain 1 and apolipoprotein E, showed association with age-related cataract." (PMID 19649315, 2009).
bacterial infections (1 paper, 2022). "KLC1 was shown to be active in viral, e.g., poxvirus, and bacterial infections, e.g., Salmonella, during the host-pathogen interactions." (PMID 35743950, 2022).
brain disease (1 paper, 2015). "As the result, the three genes (ATP1A1 for BD, RBFOX1 for BD, and KLC1 for AD and PD) are directly related to brain diseases." (PMID 26043779, 2015). "Moreover, 10 genes (ATP1A1, ATP6V1D, C16orf45, CROCC, KLC1, LUC7L2, PIAS2, PRKAR1B, RBFOX1, and RPL19) interacts with at least one brain disease-associated gene." (PMID 26043779, 2015).
KLC1 also shares sentences with these, for which no sentence is quoted: amyotrophic lateral sclerosis (2 papers); osteosarcoma (2); adenocarcinoma in situ of the lung (1); age (1); Age-related cataract (1); breast tumors (1); bronchioloalveolar carcinoma (1); cleft lip (1); coronary artery disease (1); dengue virus infection (1); diabetic neuropathy (1); Down syndrome (1); generalized dystonia (1); Intellectual disability (1); large cell lymphomas (1); melanoma (1); myoclonus and (1); pancreatic cancer (1); Parkinsonism (1); psychiatric disorder (1); renal carcinoma (1).